ELOVL2 (ELOVL fatty acid elongase 2)
Description:
Catalyzes the first and rate-limiting reaction of the four reactions that constitute the long-chain fatty acids elongation cycle. This endoplasmic reticulum-bound enzymatic process allows the addition of 2 carbons to the chain of long- and very long-chain fatty acids (VLCFAs) per cycle. Condensing enzyme that catalyzes the synthesis of polyunsaturated very long chain fatty acid (C20- and C22-PUFA), acting specifically toward polyunsaturated acyl-CoA with the higher activity toward C20:4(n-6) acyl-CoA. May participate in the production of polyunsaturated VLCFAs of different chain lengths that are involved in multiple biological processes as precursors of membrane lipids and lipid mediators.
Synonyms: SSC2
Tractability: Antibody: UniProt predicts a signal peptide or a membrane-spanning region. PROTAC: its protein half-life has been measured.
Target class: Enzyme; Transferase
Gene: Protein-coding gene on chromosome 6 (10,980,759 to 11,044,399, reverse strand). Ensembl gene ENSG00000197977.
Subcellular location: Endoplasmic reticulum membrane
Pathways (Reactome):
Metabolism: Linoleic acid (LA) metabolism; Synthesis of very long-chain fatty acyl-CoAs; alpha-linolenic acid (ALA) metabolism
Gene Ontology:
Molecular function: fatty acid elongase activity; protein binding; acyltransferase activity, transferring groups other than amino-acyl groups
Biological process: fatty acid elongation, polyunsaturated fatty acid; very long-chain fatty acid biosynthetic process; alpha-linolenic acid metabolic process; fatty acid elongation, monounsaturated fatty acid; fatty acid elongation, saturated fatty acid; linoleic acid metabolic process; long-chain fatty-acyl-CoA biosynthetic process; sphingolipid biosynthetic process; fatty acid biosynthetic process; fatty acid elongation; unsaturated fatty acid biosynthetic process
Cellular component: endoplasmic reticulum; endoplasmic reticulum membrane; membrane
Genetic constraint (gnomAD): Loss-of-function variants: 38 observed, 37.29 expected, observed/expected ratio (o/e) 1.02, 90% interval 0.79 to 1.34. The upper end of that interval is the gene's LOEUF score, 1.34, which puts it in group 5 of 6, group 1 being the genes least tolerant of losing a copy. Missense variants: 349 observed, 377.32 expected, observed/expected ratio (o/e) 0.92, 90% interval 0.85 to 1.01. Synonymous variants: 115 observed, 128.62 expected, observed/expected ratio (o/e) 0.89, 90% interval 0.77 to 1.04.
Homologues: Orthologues: chimpanzee ELOVL2 (99% identical), macaque ELOVL2 (99% identical), dog ELOVL2 (95% identical), rabbit ELOVL2 (94% identical), pig ELOVL2 (93% identical), rat Elovl2 (90% identical), mouse Elovl2 (89% identical), guinea pig ELOVL2 (88% identical), tropical clawed frog elovl2 (76% identical), zebrafish elovl2 (66% identical). Paralogues in human: ELOVL5 (55% identical), ELOVL4 (41% identical), ELOVL7 (38% identical), ELOVL1 (31% identical), ELOVL3 (22% identical), ELOVL6 (21% identical).
Diseases named in the same sentence as ELOVL2 in open-access papers:
ELOVL2 is named in the same sentence as 56 diseases in open-access papers, as found by Europe PMC text mining. Sharing a sentence is not in itself a finding about the gene and the disease. The quoted sentences say what the papers report.
breast carcinoma (14 papers, 2016 to 2026). "On a cellular model, it was shown that ELOVL2 downregulation is associated with an increased likelihood of metastasis in breast cancer." (PMID 36230586, 2022). "ELOVL2 expression was associated with malignant phenotypes and suggested as a novel prognostic biomarker in breast cancer." (PMID 36230586, 2022). "Collectively, ELOVL2 expression is associated with the malignant phenotypes and appear to be a novel prognostic biomarker in breast cancer." (PMID 30949448, 2019). "Here, we demonstrated that the downregulation of ELOVL2 increases SREBP1 expression in breast cancer cells and activates lipogenesis, which is associated with malignant phenotypes of breast cancer." (PMID 30949448, 2019). "Lower levels of ELOVL2 expression were associated with a higher grade of breast cancer and lower metastatic relapse-free survival over a 10-year period." (PMID 30949448, 2019). "This provides evidence that the ERE1 site in the Elovl2 promoter is indeed interacting with ERα in breast cancer cells and that the association is ligand dependent." (PMID 27788154, 2016). "Finally, ELOVL2 seems to be a novel prognostic biomarker of which its attenuation is significantly associated with a worse outcome of the cancer patients, including breast cancer." (PMID 30949448, 2019). "Collectively, we demonstrated a strong evidence that the down-regulation of ELOVL2 expression could be associated with the aggressiveness and progression of breast cancer and it was inferred that the tumor suppression mechanism of ELOVL2 was associated with lipid metabolism." (PMID 30949448, 2019). "Finally, ELOVL2 was later found to be down-regulated in the more aggressive phenotypes of breast cancer among 51 cell lines and associated with the clinically worse outcome of breast cancer patients." (PMID 30949448, 2019). "In conclusion, ELOVL2 overexpression inhibits HER2-positive breast cancer cell proliferation by inhibiting the PI3K-AKT pathway." (PMID 41383978, 2026). "In breast cancer, ELOVL2 acts as a tumor suppressor by attenuating tamoxifen resistance, whereas in renal cell carcinoma, it promotes tumor progression by inhibiting apoptosis." (PMID 40552308, 2025). "Knockdown of ELOVL2 induced reprogramming of lipid metabolism in breast cancer and contributed to its malignant phenotype." (PMID 37154982, 2023). "Elongation of very-long chain fatty acid protein 2 (ELOVL2) was hypermethylated and downregulated in tamoxifen-resistant breast cancer patients as compared with the tamoxifen-sensitive patients." (PMID 35853971, 2022). "ELOVL2 expression has been correlated with the malignant phenotype of breast cancer, and its downregulation induces lipid metabolism reprogramming; thus, ELOVL2 is a novel prognostic biomarker." (PMID 33278864, 2021). "A subsequent large-scale analysis using 51 breast cancer cell lines demonstrated the reduced expression of ELOVL2 in basal-like phenotypes." (PMID 30949448, 2019). "Our findings regarding the contribution of ELOVL2 to the malignant phenotypes of breast cancer were further explored by two large-scale analyses." (PMID 30949448, 2019). "Further mechanistic study discovered a novel process that the depletion of ELOVL2 increased the malignant phenotypes of breast cancer." (PMID 30949448, 2019). "In the MCF7 cell line that models breast cancers requiring estrogen for growth, ELOVL2 expression is positively regulated by estrogen, and its knockdown is associated with epithelial to mesenchymal transition." (PMID 31619292, 2019). "Breast cancer patients with low ELOVL2 expression exhibited poor prognoses (HR = 0.76, CI = 0.67–0.86)." (PMID 30949448, 2019). "For patients with breast cancer, ELOVL2 can be hormonally upregulated by the estrogen receptor alpha (ERα), and this upregulation contributes to tumor development." (PMID 31856871, 2019). "ELOVL2 is a novel tumor suppressor with low expression in breast cancer." (PMID 41383978, 2026).
breast carcinoma (continued). "Therefore, in the present study, the molecular mechanisms of the key gene ELOVL2 in HER2-positive breast cancer were preliminarily explored." (PMID 41383978, 2026). "However, ELOVL2 displayed a heterogeneous role in the prognostic value in breast cancer (BC) and glioma, respectively." (PMID 37483592, 2023). "Additionally, the down-regulated ELOVL2 can be utilized as a prognostic biomarker for breast cancer patients." (PMID 30949448, 2019). "Moreover, ELOVL2 expression was consistently reduced in breast cancer patients with basal-like status (N = 1,144) compared to that in patients with non-basal-like status (N = 4,205)." (PMID 30949448, 2019). "In conclusion, the present study demonstrates that there is a global alteration of the lipid composition during EMT and suggests the down-regulation of ELOVL2 induces lipid metabolism reprogramming in breast cancer and contributes to their malignant phenotypes." (PMID 30949448, 2019). "In conclusion, we explored a global change on the lipidome of breast cancer during EMT as well as discovered the novel effects of ELOVL2 attenuated gene expression in fatty acid biosynthesis, which may enhance the malignant phenotypes of breast cancer." (PMID 30949448, 2019). "Hence, to further examine the roles of ELOVL2 in breast cancer cells, we introduced short hairpin RNAs (shRNAs) to silence ELOVL2 in breast cancer cells." (PMID 30949448, 2019). "Furthermore, the depletion of ELOVL2 induced metastatic characteristics in breast cancer cells via the SREBPs axis." (PMID 30949448, 2019). "First, the analysis of a previous microarray dataset consisting of 51 breast cancer cell lines showed a significant attenuation of ELOVL2 expression in basal-like breast cancer cell lines associated with EMT (Basal A and Basal B) compared to luminal breast cancer cell lines." (PMID 30949448, 2019). "Notably, our findings implicate ELOVL2 depletion in breast cancer progression." (PMID 30949448, 2019). "Our study constructed the prognostic signature based on breast cancer PD-1/PD-L1 pathway molecular typing-related genes (IFNG, JCHAIN, ELOVL2, PIGR, PAGE5, ACTL8, and CLEC3A)." (PMID 37154982, 2023). "Insights in the mechanisms whereby Elovl2 mRNA levels can be regulated can have implications on DHA production and its protective effects in breast cancer patients." (PMID 27788154, 2016). "Our data implies that the accessibility of ERα ligand is enough to enhance Elovl2 expression and DHA formation in breast cancer cells." (PMID 27788154, 2016). "Previous researches showed that the expression of ELOVL2 was robustly up-regulated upon estradiol stimulation in human breast cancer cell line which expresses ERα but not ERβ, and was almost fully eliminated by knock-down of ERα." (PMID 36253734, 2022). "The involvement of ERα in the control of especially Elovl2, which plays a crucial role in DHA synthesis, may have potential implications in the treatment of breast cancer." (PMID 27788154, 2016). "Therefore, discerning the mechanism of action of ELOVL2, that has the potential to specifically modulate DHA availability, would be useful to unravel means to reduce cell viability in breast cancer." (PMID 27788154, 2016).
prostate carcinoma (10 papers, 2017 to 2026). A carcinoma that arises from epithelial cells of the prostate gland. "In prostate cancer, ELOVL2 showed a notable upregulation in SPOP mutations that mediate drug resistance." (PMID 31856871, 2019). "On the opposite, ELOVL2 upregulation in prostate cancer has been associated with the oncogenic effect of SPOP loss of function mutations." (PMID 31619292, 2019). "To further investigate the functional role of ELOVL2 in prostate cancer (PCa), we employed siRNA-mediated knockdown to deplete ELOVL2 expression in enzalutamide-resistant LNCaP-enzR and C4-2-enzR cells." (PMID 40552308, 2025). "The expression of particular elongases (e.g. ELOVL2 in glioma or ELOVL5 in prostate cancer) supports cell growth, tumor initiation and metastasis." (PMID 36857618, 2023). "Previously, several studies have been reported that FH is frequently mutated in renal cancer, ELOVL2 is upregulated in hepatocellular cancer, and ACADL is associated with prostate cancer progression." (PMID 29262542, 2017). "In prostate cancer, high expression of ELOVL2 suggests improved prognosis, and small hairpin RNA targeting ELOVL2 promotes cell proliferation, colony formation, migration and invasion, as well as the growth of subcutaneous xenografts by activating the PI3K/AKT signaling pathway." (PMID 41383978, 2026). "ELOVL2 inhibited cell proliferation, migration, and invasion in prostate cancer (PC) and may act as a novel tumor suppressor to attenuate tamoxifen resistance in BC; however, in renal cell carcinoma (RCC), ELOVL2 promoted cancer progression by inhibiting apoptosis." (PMID 36823639, 2023). "There is one study where in the human prostate cancer cell line (LNCaP) with the knockdown of ELOVL2, ELOVL5, or ELOVL7, no compensatory increases in the expression of the other ELOVLs were observed in the cancer cell line, and no normal cell line was analyzed." (PMID 38139442, 2023).
glioma (8 papers, 2020 to 2025). A benign or malignant brain and spinal cord tumor that arises from glial cells (astrocytes, oligodendrocytes, ependymal cells). "A higher ELOVL2 expression in the tumor is associated with a worse prognosis for patients with GBM and glioma." (PMID 36291290, 2022). "Regarding the ACACA and ELOVL2 genes, we observed that these two genes were overexpressed in all glioma samples, and there was a relationship between the degree of tumor and expression." (PMID 34573317, 2021). "Recent studies have shown that blocking key enzymes of fatty acid synthesis, such as fatty acid synthase (FASN) and ELOVL fatty acid elongase 2 (ELOVL2), suppressed glioma tumor growth in GBM xenograft models, further suggesting the importance of fatty acids for glioma growth and survival." (PMID 35513201, 2022).
Obesity (8 papers, 2016 to 2023). Accumulation of substantial excess body fat. "Polymorphisms in FA elongase (ELOVL2) are associated with Alzheimer’s disease, Autism spectrum disorder and obesity." (PMID 36900123, 2023). "Our findings are underlying several other studies on identifying genetic variants in the ELOVL2 gene associated with obesity-related conditions." (PMID 35276915, 2022). "Similarly, in another study carried out in Italian children and adolescents, a similar behavior was observed in the association of genetic variants of ELOVL2 with indicators of obesity and insulin resistance, in addition to alterations in the blood lipid profile." (PMID 33158152, 2020). "However, expanding to test the whole pathway using a multi-set approach does detect significant associations at the pathway level, allowing us to examine more closely the individual gene tests, identifying potentially novel associations between FFAR2 and ELOVL2 with obesity." (PMID 33240333, 2020). "Therefore, higher ELOVL2 expression may be a risk factor for the development of obesity and associated co-morbidities for individuals with prior pre-natal SGA condition." (PMID 27631473, 2016). "Altered circulating ELOVL2/5 elongase activity has been observed in patients with a metabolic syndrome related to overweight/obesity." (PMID 35625732, 2022). "Several studies have identified the association between genetic variants in the FADS2 and ELOVL2 genes controlling endogenous PUFA synthesis and obesity-related conditions in adults and children." (PMID 35276915, 2022). "A two-week pre-treatment of DHA-supplemented diet prior to the high fat exposure was able to restore systemic levels of DHA to normal, which also abolished the resistance to diet-induced obesity in the Elovl2 -/- mice." (PMID 30991731, 2019). "Elovl2 -/- animals are resistant to diet-induced obesity, and administration of dietary DHA in those mice resulted in fully recovered DHA levels as well as weight gain." (PMID 30991731, 2019). "UCP1-KO as well as fatty acid elongase-2 (Elovl2)-KO mice require housing under thermoneutrality to reveal the obesity phenotype." (PMID 29848963, 2018). "Moreover, Elovl2 KO animals show metabolic changes (lower respiratory quotient) and resistance to diet-induced obesity, suggesting a potential role of mitochondria in regulating these metabolic processes." (PMID 35276915, 2022).
diabetes (7 papers, 2014 to 2025). "Furthermore, silencing ELOVL2 through methylation or ELOVL2 protein depletion accelerates aging in the mouse retina and has been linked to diabetes, as well as increased risk of breast and male colorectal cancer." (PMID 40244262, 2025). "In their studies, retinal DHA reductions in diabetes were linked to lowered expression of ELOVL2 and ELOVL4, although the mechanism for suppressed expression of these factors remains unclear." (PMID 34425110, 2021). "Taken together, these results demonstrate that genes centrally involved in the regulation of lipid metabolism, srebp1c, PPARγ and PPARα, Elovl4 and Elovl2 have daily rhythms of expression profile in the retina and their daily rhythms are perturbed by diabetes." (PMID 24736612, 2014). "Second, the synthesis of DHA in the retina may be impaired in diabetes, because the expression of ELOVL2, which is needed for the conversion of EPA to DHA, has been shown to be reduced by >25% in diabetic mice compared to the non-diabetic controls." (PMID 39728692, 2024).
glioblastoma (6 papers, 2019 to 2023). The most malignant astrocytic tumor (WHO grade IV). "ELOVL2 importance for GBM is strengthened by a study published during writing of this article that describes ELOVL2 as a super-enhancer associated gene controlling glioblastoma stem cell properties." (PMID 31619292, 2019). "In vivo studies have shown that decreasing Elovl2 expression in glioblastoma tumors inhibits tumor growth." (PMID 37046844, 2023). "Studies on glioblastoma patients have also demonstrated the crucial role of Elovl2 in the aggressiveness of this tumor." (PMID 37046844, 2023). "Elovl2 expression differs depending on the glioblastoma cell type." (PMID 37046844, 2023). "The expression of Elovl2 in glioblastoma tumors may increase or remain at a similar level to that in healthy brain tissue." (PMID 37046844, 2023). "For instance, ELOVL2 was identified as an unique tissue-independent age-associated DNA methylation marker and a specific superenhancer-associated gene implicated the LC-PUFA synthesis network as a critical metabolic dependency, and was associated with worsened patient survival in glioblastoma." (PMID 37483592, 2023). "Interestingly, the expression of Elovl2 in glioblastoma tumors may be lower in female patients than in male patients." (PMID 37046844, 2023). "We also examined the effect of GZ17-6.02 on recently identified glioblastoma super-enhancer genes WSCD1, EVOL2, and KLHDC8A as well as the enzyme FADS2, which mediates ELOVL2 signaling." (PMID 35456993, 2022). "The production of this PUFA mainly occurs in glioblastoma cancer stem cells, which possess higher expression of Elovl2 than glioblastoma cancer nonstem cells." (PMID 37046844, 2023). "In contrast, ELOVL2 depletion altered the phospholipid composition of the cell membrane by controlling fatty acid elongation, disrupting the structural characteristics of the cell membrane, and reducing EGFR signaling in glioblastoma cells." (PMID 37483592, 2023). "In differentiated glioblastoma cells, the expression of Elovl2 is low, and it does not play any significant role in these cells." (PMID 37046844, 2023).
Hepatic steatosis (5 papers, 2014 to 2025). Steatosis is a term used to denote lipid accumulation within hepatocytes. "Future studies of mitochondria in Elovl2 KO mice on a high-fat diet would help establish the possible link between resistance to oxidative damage and resistance to hepatic steatosis." (PMID 35276915, 2022). "We selected genes related to fat metabolism and fatty liver disease for these analyses, including FADS2 encoding Δ-6 desaturase and ELOVL2 encoding long chain fatty acid elongase, which are important rate-limiting enzymes in the synthesis of polyunsaturated fatty acids." (PMID 33571255, 2021). "Moreover, Elovl2 KO mice are resistant to hepatic steatosis induced by a high-fat diet." (PMID 35276915, 2022). "Surprisingly, the Elovl2−/− mice were resistant to hepatic steatosis and diet-induced weight gain, implying that hepatic DHA synthesis via ELOVL2, in addition to controlling de novo lipogenesis, also regulates lipid storage and fat mass expansion in an SREBP-1c-independent fashion." (PMID 24489111, 2014).